NFAT5 (nuclear factor of activated T cells 5)
Diseases named in the same sentence as NFAT5 in open-access papers (continued):
Sharing a sentence is not in itself a finding about the gene and the disease.
renal carcinoma (6 papers, 2014 to 2025). A carcinoma arising from the epithelium of the renal parenchyma or the renal pelvis. "Crucially, NFAT5 knockdown alone resulted in a dramatic increase their basal expression, indicating that in this specific renal cancer context, NFAT5 functions as a transcriptional repressor of these metabolic genes." (PMID 41584586, 2025). "It has been recently shown that in renal cancer Nfat5 expression is targeted by microRNAs that led to reduced expression of Nfat5 target genes." (PMID 32059438, 2020). "Since Vhl deletion alone did not induce renal cancer in mice model, it might be interesting to test if a Vhl/Nfat5 double KO develops renal cancer." (PMID 32059438, 2020).
thymoma (6 papers, 2016 to 2025). A neoplasm arising from the epithelial cells of the thymus. "Recent studies identified that several miRNAs can target Nfat5. miR-20b was studied in thymoma-associated myasthenia gravis, where it inhibited NFAT5 expression with reduced T cell proliferation." (PMID 30538703, 2018). "In MG and thymoma-associated MG, miR-20b is downregulated, leading to increased NFAT5 expression." (PMID 40421201, 2025). "Similarly, miRNA-20b was found to be down-regulated in patients with thymoma-associated MG and to target Nuclear Factor of Activated T-cells 5 (NFAT5) and Calmodulin Binding Transcription Activator 1 (CAMTA1), thus inhibiting T-cell proliferation and activation." (PMID 35409405, 2022). "To determine the physiological significance of miR-20b targeting NFAT5 and CAMTA1, we assessed the expression levels of miR-20b, NFAT5, and CAMTA1 in thymoma tissue specimens from 30 thymoma-associated myasthenia gravis patients." (PMID 27833920, 2016). "Given that miR-20b directly targets NFAT5, its downregulation may act as a tumor suppressor mechanism, potentially explaining thymoma progression in MG patients." (PMID 40421201, 2025). "The tumor suppressive function of miR-20b in thymoma could be due to its inhibition of NFAT signaling by repression of NFAT5 and CAMTA1 expression." (PMID 27833920, 2016).
chronic kidney disease (5 papers, 2020 to 2025). Impairment of the renal function secondary to chronic kidney damage persisting for three or more months. "NFAT5 is upregulated, for instance, by high phosphate levels in plasma and tissue as prevalent during chronic kidney disease, a disease, which is also directly linked to cardiovascular events." (PMID 35203269, 2022). "Our study provides two major findings: First, Nfat5 deficiency alone in the distal nephron is sufficient to cause severe kidney fibrosis that represents the common pathological feature and signs of chronic kidney disease (CKD)." (PMID 39874047, 2025). "miR-381-3p in BMSC-Exo could alleviate vascular calcification in chronic kidney disease by targeting NFAT5." (PMID 38444939, 2024). "Impairment of renal phosphate elimination in chronic kidney disease (CKD) leads to enhanced plasma and tissue phosphate concentration, which in turn up-regulates transcription factor NFAT5 and serum & glucocorticoid-inducible kinase SGK1." (PMID 32015442, 2020).
non-small cell lung carcinoma (5 papers, 2014 to 2025). A group of at least three distinct histological types of lung cancer, including non-small cell squamous cell carcinoma, adenocarcinoma, and large cell carcinoma. "For example, lncRNA RMRP can promote the proliferation and invasion of non-small cell lung cancer through miR-613/NFAT5 pathway." (PMID 39925803, 2025). "In non-small cell lung cancer, NFAT5-mediated upregulation of HSP70 confers enhanced resistance against apoptosis on tumor cells by inhibition of lysosomal membrane permeabilization." (PMID 25152734, 2014).
periodontitis (5 papers, 2021 to 2025). An acute or chronic inflammatory process that affects the tissues that surround and support the teeth. "In periodontitis, NFAT5 gene expression is downregulated compared to healthy gingival tissue, accompanied by upregulation of miRNA-20a, miRNA-30e, and miRNA-93, suggesting a potential post-transcriptional regulatory mechanism." (PMID 40421201, 2025). "The 3D culture system improved the functionality of MSC-Exo for the treatment of periodontitis, and 3D-Exo exhibited greater enrichment of miR-1246, which inhibits the expression of Nfat5 of Th17, and in turn treats periodontitis more effectively." (PMID 38129853, 2023). "The concentration of mRNA obtained from NFAT5 was significantly lower in periodontitis biopsies compared to healthy gingival tissue (p = 0.037)." (PMID 36142220, 2022). "The present study aimed to explore the expression of inflammatory hypoxia-related miRNAs (miRNA-20a, miRNA-30e, and miRNA-93), and miRNA target genes, HIF-1α and NFAT5, in periodontitis and healthy gingival tissues." (PMID 36142220, 2022). "In conclusion, in periodontitis patients, the expression of miRNA-20a, miRNA-30e, and miRNA-93 increased, but a decreased expression of NFAT5 mRNA was detected." (PMID 36142220, 2022). "In the current study, we found an increased expression of miRNA-20a, miRNA-30e, miRNA-93, and decreased levels of NFAT5 mRNA in periodontitis biopsies, which should be investigated in greater depth." (PMID 36142220, 2022). "The 3D-exos contained more miR-1246, which can mediate CD4+ T-cell differentiation by decreasing Nfat5, thereby relieving Th17 cell/Treg imbalance and alleviating periodontitis." (PMID 34907166, 2021). "The objective of the present study was to explore hypoxia-related miRNA target genes for HIF-1α and NFAT5, as well as miRNA-20a, miRNA-30e, and miRNA-93 expression in periodontitis versus healthy gingival tissues and gingival mesenchymal stem cells (GMSCs) cultured under hypoxic conditions." (PMID 36142220, 2022). "However, in the present study, we found a downregulation of NFAT5 expression in periodontitis biopsies." (PMID 36142220, 2022). "Thus, the upregulation of these inflammatory and hypoxia-related miRNAs, accompanied by an NFAT5 mRNA downregulation, could be involved in periodontitis pathogenesis, and this should be examined in greater depth in further studies." (PMID 36142220, 2022). "However, the levels of HIF-1α mRNA were similar in both groups, suggesting that the studied miRNAs (miRNA-20a, miRNA-30e, and miRNA-93) could be involved in the downregulation of NFAT5 in periodontitis tissues." (PMID 36142220, 2022). "Periodontitis aggravates IBD and MSC-EXO produced by 3D culture promotes the expression of miR-1246, inhibits Nfat5, restores Th17 cell/Treg balance, and relieves the periodontitis of IBD patients." (PMID 37261347, 2023). "Taken together, these results indicate that by targeting Nfat5, miR-1246 transferred by DPSC-exos contributes to restoring the Th17 cell/Treg balance, thereby alleviating periodontitis and IBD." (PMID 34907166, 2021). "NFAT5 mRNA was downregulated in periodontitis tissues (p = 0.037), but HIF-1α was not affected (p = 0.60)." (PMID 36142220, 2022). "Furthermore, our results suggest that NFAT5, but not HIF-1α mRNA, was downregulated in periodontitis patients, suggesting that the activation of miRNAs is potentially associated with NFAT5 expression in periodontal tissues." (PMID 36142220, 2022).
systemic lupus erythematosus (5 papers, 2019 to 2025). An autoimmune multi-organ disease typically associated with vasculopathy and autoantibody production. "Additionally, pathogenic NFAT5 variants have been identified in 14 families with familial autoimmunity, encompassing primary Sjögren's syndrome (pSS), systemic lupus erythematosus (SLE), and RA, underscoring its role in genetic predisposition to autoimmunity." (PMID 40421201, 2025). "NFAT5-dependent TLR activation on macrophages seemed to be responsible for the unresponsiveness in these lupus mice." (PMID 38256157, 2024). "This is also the case for prolidase D (PEPD) deficiency, which has been associated with the development of systemic lupus erythematosus (SLE), and zeta chain of T cell receptor-associated protein kinase 70 (ZAP-70) and nuclear factor of activated T cells 5 (NFAT5) deficiencies." (PMID 31849949, 2019). "Pristane-lupus mice with myeloid lineage-depletion of NFAT5 failed to develop lupus and LN." (PMID 38256157, 2024). "Furthermore, in a mice model of pristane-induced systemic lupus erythematosus (SLE), the absence of NFAT5 in myeloid cells prevented the development of LN and SLE." (PMID 37287987, 2023).
Autoimmunity (4 papers, 2019 to 2025). The occurrence of an immune reaction against the organism's own cells or tissues. "This section explores the connection between NFAT5 and autoimmunity, highlighting its involvement in disease pathogenesis and potential therapeutic implications." (PMID 40421201, 2025). "As a primary immunodeficiency syndrome, NFAT5 haploinsufficiency was recently described primarily presenting with IBD and autoimmunity, however, further published data on affected patients and on alloHSCT are not available to date." (PMID 31799221, 2019).
co-infection (4 papers, 2012 to 2020). "NFAT5 has also been found to play a crucial role in M.tb regulation of HIV-1 replication on co-infection via a direct interaction with the viral promoter." (PMID 24586438, 2014). "This identification of a novel role for NFAT5 in TB/HIV-1 co-infection reveals that NFAT5 is a major mediator of TLR-dependent gene expression and thus provides a potential new therapeutic target for treatment of HIV-1 and possibly other diseases." (PMID 22496647, 2012). "We thus next extended our analysis of the role of NFAT5 in MTb/HIV-1 co-infection to a subtype C isolate." (PMID 22496647, 2012). "To extend the results we obtained in the reporter assays to a physiological TB/HIV co-infection model, we next tested the effect of siRNA-mediated ablation of NFAT5 mRNA levels in MDM co-infected with a subtype B HIV-1Lai infectious molecular clone and a clinical isolate of MTb." (PMID 22496647, 2012). "However, the replication of each mutant virus was impaired to a more significant extent in the context of MTb co-infection, consistent with important roles for both NF-κB and NFAT5 in MTb-induced HIV-1 replication." (PMID 22496647, 2012). "In this report we directly examined the relative roles of NFAT5 and NF-κB p50/p65 in HIV-1 replication under conditions of activation by MTb co-infection, when NF-κB levels in the nucleus are elevated." (PMID 22496647, 2012). "In conclusion, we have demonstrated that NFAT5 is required for the replication of R5-tropic subtype B and subtype C HIV-1 isolates in response to MTb-co-infection of human PBMC and MDM." (PMID 22496647, 2012).
Cognitive impairment (4 papers, 2021 to 2025). Abnormal cognition is characterized by deficits in thinking, reasoning, or remembering. "Notably, NFAT5 haploinsufficiency reduces microglial activation and mitigates cognitive impairment in middle-aged mice, positioning NFAT5 as a key driver of neuroinflammatory changes associated with aging." (PMID 40421201, 2025).
diabetic retinopathy (4 papers, 2019 to 2026). "Consistently, in streptozotocin-induced diabetic retinopathy, NFAT5 deficiency decreases AR expression and alleviates the retinopathy." (PMID 30873159, 2019). "Mice injected with NFAT5 siRNA showed reduced streptozotocin-induced diabetic retinopathy." (PMID 33015193, 2020). "Additionally, NFAT5 upregulates retinal ganglion cell apoptosis in diabetic retinopathy." (PMID 33015193, 2020).
Duchenne muscular dystrophy (4 papers, 2020 to 2025). Duchenne muscular dystrophy (DMD) is a neuromuscular disease characterized by rapidly progressive muscle weakness and wasting due to degeneration of skeletal, smooth and cardiac muscle. "In Duchenne muscular dystrophy (DMD), a chronic idiopathic inflammatory myopathy, NFAT5, SMIT, AR, and TauT are overexpressed compared to controls, implicating this osmoregulatory-proinflammatory pathway in chronic muscle inflammation." (PMID 40421201, 2025).
endothelial dysfunction (4 papers, 2020 to 2023). In vascular diseases, endothelial dysfunction is a systemic pathological state of the endothelium (the inner lining of blood vessels) and can be broadly defined as an imbalance between vasodilating and vasoconstricting substances produced by (or acting on) the endothelium. "Overexpression of miR-486-5p can prevent endothelial dysfunction, and the mechanism might be related to anti-inflammation and anti-oxidation via targeting NFAT5." (PMID 35322734, 2022). "MiR-486-5p can prevent endothelial dysfunction, and the mechanism might be related to anti-inflammation and anti-oxidative via targeting NFAT5." (PMID 35322734, 2022). "Notably, we further validated that NFAT5 could significantly accelerate endothelial dysfunction by binding to the PAI-1 promoter and activating PAI-1 expression under HS conditions." (PMID 33410782, 2020). "Our study showed that HS intake activates NFAT5 to elevate PAI-1 secretion in ECs, which promotes fibrin deposition and macrophages infiltration into artery wall of mice, suggesting that NFAT5 is a key regulator of endothelial dysfunction in reducing AS." (PMID 33410782, 2020).
epithelial ovarian cancer (4 papers, 2021 to 2025). "Concluding, the presence of NFAT5 in the cytoplasm as an inactive transcription factor was linked to prognostically favorable clinical and pathological characteristics of epithelial ovarian cancer." (PMID 34631538, 2021). "Moreover, increased cytoplasmic NFAT5 expression in ovarian cancer specimens is associated with more favourable clinical and pathological outcomes." (PMID 40421201, 2025). "Basal NFAT5 expression is notably elevated in epithelial ovarian cancer cell lines (ES-2, OVCAR3, TOV112D, and UWB1.289), while NFAT5 silencing reduces viability, proliferation, and migration, particularly in UWB1.289 cells." (PMID 40421201, 2025). "Regarding NFAT5 gene expression, comparable results were achieved by showing that high NFAT5 gene expression (nhigh=152) is significantly correlated with an impaired prognosis of ovarian cancer patients (nlow= 221; p=0.027)." (PMID 34631538, 2021). "The present study aimed at elucidating the functional role of ACTBL2 and NFAT5 in epithelial ovarian cancer, intentionally assisting to obtain new findings on its etiology with regard to carcinogenetic and disease-promoting mechanisms." (PMID 34631538, 2021). "In vitro analyses of NFAT5 in ovarian cancer revealed a significantly elevated mRNA expression in UWB1.289 cells, again being highest compared to other tested malignant cell lines." (PMID 34631538, 2021). "Aiming to assess molecular biological mechanisms regulating the function of ACTBL2, the impact of NFAT5 on ovarian cancer cells was further investigated." (PMID 34631538, 2021). "The expression of ACTBL2 and NFAT5 was examined in tissue microarrays of 156 ovarian cancer patients by immunohistochemistry." (PMID 34631538, 2021). "Concluding, the present study investigated the carcinogenetic and prognostic impact of ACTBL2 and NFAT5 in epithelial ovarian cancer by elucidating their expression pattern in EOC patients and their functional molecular interplay in vitro." (PMID 34631538, 2021). "In sum, our results show for the first time a functional relation between NFAT5 and ACTBL2 in ovarian cancer, with NFAT5 silencing regulating the effect of ACTBL2 on cellular functions, predominantly resulting in a decreased migratory potential of UWB1.289 cells." (PMID 34631538, 2021). "In comparison, macrophages expressing NFAT5 are more prone to polarize toward a Th1 proinflammatory phenotype, characterized by increased IL12, Fizz-1, and arginase 1 expression, compared to Lewis lung carcinoma and ID8 ovarian carcinoma cells." (PMID 40421201, 2025). "Further studies evaluating the targeted antiproliferative use of Etomoxir are necessary to precisely analyze its impact on NFAT5 and ACTBL2 expression in vitro and in vivo with special regard to consecutively altered cellular functions in epithelial ovarian cancer." (PMID 34631538, 2021). "An additionally performed correlation analysis of ACTBL2 and NFAT5 expression using the TIMER database revealed a positive correlation trend between both genes (Cc=0.103, p=0.073), hinting at their previously outlined functional relation in epithelial ovarian cancer." (PMID 34631538, 2021).
inflammatory bowel disease (4 papers, 2018 to 2024). A spectrum of small and large bowel inflammatory diseases of unknown etiology. "In this section we discuss diseases with a distinc phenotype of inflammatory bowel disease including the “IL-10 group” of IL-10 and IL-10 receptor alpha and beta deficiency as well as the haploinsufficincy of NFAT5." (PMID 31799221, 2019).
ischemia (4 papers, 2015 to 2025). A hypoperfusion of the BLOOD through an organ or tissue caused by a PATHOLOGIC CONSTRICTION or obstruction of its BLOOD VESSELS, or an absence of BLOOD CIRCULATION. "In contrast to our results, a previous study demonstrated that the heterozygous (NFAT5+/−) mice exhibited more pronounced cerebral edema and larger cerebral infarction after hypoxia/ischemia compared with wild-type mice." (PMID 40831534, 2025). "Thus far, our results suggested that NFAT5 maintains the baseline Kir2.1 level prior ischemia or reperfusion." (PMID 39710754, 2024). "Likewise, the stress-responsive transcription factor Nuclear factor of activated T-cells 5 (NFAT5 or tonicity enhancer binding protein (TonEBP) was shown to be relevant for coping with the environmental stress following ischemia." (PMID 39710754, 2024).
liver cancer (4 papers, 2017 to 2025). An epithelial or non-epithelial malignant neoplasm that arises from the liver. "Interestingly, HBV enhanced liver cancer progression by suppressing NFAT5." (PMID 33330488, 2020). "The results indicated that aberrant expression of NFAT5 was negatively correlated with the histologic grade (P = 0.035), HBV infection (P < 0.01) and the Barcelona Clinic Liver Cancer (BCLC) stage (P < 0.01)." (PMID 29052520, 2017). "Subsequently, the low expression of NFAT5 could up-regulate aspartyl-tRNA synthetase 2 (DARS2), thereby promoting liver cancer development by accelerating cell cycle progression and inhibiting cell apoptosis." (PMID 33330488, 2020).
myocarditis (4 papers, 2017 to 2025). Myocarditis is a condition that is characterized by inflammation of the heart muscle (myocardium). "As CVB3 is a cardiotropic virus and a predominant pathogenic cause of myocarditis, it is important to understand the role of NFAT5 in CVB3-infected cardiomyocytes." (PMID 29220410, 2017). "Nuclear factor of activated T cells 5 (NFAT5), an osmosensitive transcription factor, has been shown to protect against coxsackievirus B3 (CVB3)-induced myocarditis but is susceptible to cleavage by viral proteases." (PMID 41156753, 2025). "Taken together, our findings have uncovered a novel anti-CVB3 role of NFAT5 and provided a promising drug target for CVB3-induced myocarditis." (PMID 29220410, 2017). "Our findings demonstrate that miR-93-3p directly targets 3′UTR of EIF4EBP1, consistent with prior studies showing that miR-93-3p alleviates renal injury by targeting NFAT5, promotes cellular proliferation and migration via targeting ZFP36L1, and modulates myocarditis by regulating TLR4 expression." (PMID 40900833, 2025). "The collection of evidence demonstrates that CVB3-induced myocarditis can impair cardiac function by cleaving host proteins involved in the immune response, including MAVs, TRIF, NFAT5, SQSTM1, and CARD8, to impair host defense mechanisms and promote pyroptosis and apoptosis." (PMID 37175422, 2023). "Thus, in this study, we used the myocarditis models of CVB3 infection of both a cardiomyocyte cell line and A/J mice to elucidate NFAT5’s role in CVB3 replication and CVB3-induced myocarditis." (PMID 29220410, 2017).